POLD2 (DNA polymerase delta 2, accessory subunit)
Description:
Accessory component of both the DNA polymerase delta complex and the DNA polymerase zeta complex. As a component of the trimeric and tetrameric DNA polymerase delta complexes (Pol-delta3 and Pol-delta4, respectively), plays a role in high fidelity genome replication, including in lagging strand synthesis, and repair. Pol-delta3 and Pol-delta4 are characterized by the absence or the presence of POLD4. They exhibit differences in catalytic activity. Most notably, Pol-delta3 shows higher proofreading activity than Pol-delta4. Although both Pol-delta3 and Pol-delta4 process Okazaki fragments in vitro, Pol-delta3 may also be better suited to fulfill this task, exhibiting near-absence of strand displacement activity compared to Pol-delta4 and stalling on encounter with the 5'-blocking oligonucleotides. Pol-delta3 idling process may avoid the formation of a gap, while maintaining a nick that can be readily ligated. Along with DNA polymerase kappa, DNA polymerase delta carries out approximately half of nucleotide excision repair (NER) synthesis following UV irradiation. Under conditions of DNA replication stress, required for the repair of broken replication forks through break-induced replication (BIR). Involved in the translesion synthesis (TLS) of templates carrying O6-methylguanine or abasic sites performed by Pol-delta4, independently of DNA polymerase zeta (REV3L) or eta (POLH). Facilitates abasic site bypass by DNA polymerase delta by promoting extension from the nucleotide inserted opposite the lesion. Also involved in TLS as a component of the DNA polymerase zeta complex. Along with POLD3, dramatically increases the efficiency and processivity of DNA synthesis of the DNA polymerase zeta complex compared to the minimal zeta complex, consisting of only REV3L and REV7.
Tractability: Small molecule: an approved drug acts on it; a structure with a bound ligand is known; it has a high-quality binding pocket. PROTAC: ubiquitination databases record sites on it; its protein half-life has been measured.
Target class: Enzyme
Gene: Protein-coding gene on chromosome 7 (44,114,631 to 44,124,407, reverse strand). Ensembl gene ENSG00000106628.
Subcellular location: Nucleus
Subcellular location (Human Protein Atlas): Nucleoplasm
Pathways (Reactome):
DNA Repair: Dual Incision in GG-NER; Dual incision in TC-NER; Gap-filling DNA repair synthesis and ligation in GG-NER; Gap-filling DNA repair synthesis and ligation in TC-NER; HDR through Homologous Recombination (HRR); PCNA-Dependent Long Patch Base Excision Repair; Recognition of DNA damage by PCNA-containing replication complex; Termination of translesion DNA synthesis
Cell Cycle: Polymerase switching on the C-strand of the telomere; Processive synthesis on the C-strand of the telomere; Removal of the Flap Intermediate from the C-strand; Telomere C-strand (Lagging Strand) Synthesis
DNA Replication: Polymerase switching; Processive synthesis on the lagging strand; Removal of the Flap Intermediate
Gene Ontology:
Molecular function: DNA polymerase binding; enzyme activator activity; protein binding; DNA binding
Biological process: DNA biosynthetic process; DNA-templated DNA replication; error-prone translesion synthesis; DNA replication; DNA strand elongation involved in DNA replication
Cellular component: delta DNA polymerase complex; nucleoplasm; nucleus; zeta DNA polymerase complex
Genetic constraint (gnomAD): Loss-of-function variants: 32 observed, 46.22 expected, observed/expected ratio (o/e) 0.69, 90% interval 0.52 to 0.93. The upper end of that interval is the gene's LOEUF score, 0.93, which puts it in group 3 of 6, group 1 being the genes least tolerant of losing a copy. Missense variants: 454 observed, 625.65 expected, observed/expected ratio (o/e) 0.73, 90% interval 0.67 to 0.78. Synonymous variants: 233 observed, 262.58 expected, observed/expected ratio (o/e) 0.89, 90% interval 0.8 to 0.99.
Gene-disease validity (ClinGen):
ClinGen rates the evidence that POLD2 causes each of these diseases.
non-severe combined immunodeficiency due to polymerase delta deficiency (autosomal recessive): Limited. Any non-severe combined immunodeficiency in which the cause of the disease is variation in the POLD1/POLD2 gene.
Homologues: Orthologues: chimpanzee POLD2 (99% identical), macaque POLD2 (99% identical), chimpanzee POLD2 (96% identical), mouse Pold2 (94% identical), rat Pold2 (94% identical), dog POLD2 (93% identical), guinea pig POLD2 (93% identical), pig POLD2 (92% identical), rabbit POLD2 (88% identical), tropical clawed frog pold2 (69% identical), zebrafish pold2 (66% identical), Drosophila melanogaster PolD2 (40% identical), and 1 more.